IGFBP1 (insulin like growth factor binding protein 1)
Diseases named in the same sentence as IGFBP1 in open-access papers (continued):
Sharing a sentence is not in itself a finding about the gene and the disease.
diabetes (60 papers, 2002 to 2025). "Alterations in IGFBP-1 phosphorylation have been linked to diabetes pregnancies and adverse fetal outcomes." (PMID 41333061, 2025). "It has previously been suggested that, in women with central adiposity, failure of IGFBP-1 to be suppressed by more than 40% after an oral glucose challenge identifies a group at high risk of increasing abdominal adiposity and diabetes." (PMID 39595651, 2024). "In the present study, there were numerous, although mostly relatively small, correlations between s-IGFBP-1 and metabolic risk factors, including diabetes, HOMA-IR, and BMI." (PMID 37298072, 2023). "The inverted U pattern of IGF-I bioactivity is probably caused by direct modulating effects of insulin (and IGFBP-1) on IGF-I bioactivity during the natural course from fasting normoglycemia to frank diabetes." (PMID 36901984, 2023). "In age- and sex-adjusted analysis, high IGFBP-1 remained significantly associated with protection from incident diabetes in the overall cohort (HR 0.50, 95% CI 0.29–0.88, p = 0.02) and in men (HR 0.31, 95% CI 0.10–0.92, p = 0.03)." (PMID 32492897, 2020). "On the other hand, high IGFBP-1 was associated with reduced diabetes risk in the overall cohort in unadjusted analysis (p = 0.01)." (PMID 32492897, 2020). "High serum IGF-1 predicted greater risk for MDCI (HR 1.56, 95% CI 1.08–2.26) and composite incident morbidity (HR 1.242, 95% CI 1.004–1.538), whereas high IGFBP-1 predicted lower risk for diabetes (HR 0.50, 95% CI 0.29–0.88)." (PMID 32492897, 2020). "In our cohort of older adults, we found in an age-adjusted analysis that low IGFBP-1 predicted risk for diabetes." (PMID 32492897, 2020). "Overexpression of IGFBP1 was suggested to affect glomerulosclerosis, and an increased hepatic production of IGFBP1 was linked to a decline in IGF1 serum levels in people with diabetes." (PMID 31772941, 2019). "This trend is the same in women: a study of 240 women, over 8 years, showed that IGFBP-1 was associated with increased risk of diabetes." (PMID 30392760, 2019). "Earlier studies showed that circulating level of IGFBP1 was associated with insulin resistance and diabetes." (PMID 28316362, 2017). "The outcomes showed that women with the lowest fasting IGFBP-1 at baseline had a higher risk for developing diabetes within 8 years, also showing an impaired IGFBP-1 suppression after oral glucose loading." (PMID 26733412, 2016). "Free IGF-I concentrations are associated with incident diabetes in women with insulin levels above, and IGFBP-1 levels below, the median." (PMID 26237614, 2014). "In middle-aged women, IGFBP1 levels rose after the onset of diabetes, indicating a loss of insulin sensitivity in the liver." (PMID 23781317, 2013). "Indeed, high IGFBP-1 predicted diabetes onset in a high-risk prediabetic cohort over two years compared to healthy population." (PMID 41226444, 2025). "IGFBP1 concentrations are associated with diabetes, and increasing IGFBP1 concentrations may be a beneficial effect of probiotic supplementation on glucose metabolism." (PMID 37960204, 2023). "While low levels of IGFBP-1 have been associated with increased risk for diabetes in middle-aged individuals, our study is among the first to show that low IGFBP-1 levels may predict diabetes in older adults." (PMID 32492897, 2020). "However, prospective data on the association between IGFBP-1 and diabetes risk in older adults are scarce." (PMID 32492897, 2020). "More recently, a low fasting IGFBP-1 concentration was shown to be predictive of the development of abnormal glucose regulation in 355 Swedish men studied over 10 years, with some having up to a 40-fold increased risk of developing diabetes." (PMID 30392760, 2019). "Moreover, increasing levels of circulating IGFBP1 have been linked to hyperglycemia, and overexpression of IGFBP1 in diabetes was shown to contribute to glomerulosclerosis." (PMID 31772941, 2019).
diabetes (continued). "This suggests a potential mechanism for IGFBP-1's protective role in preventing diabetes development." (PMID 41333061, 2025). "In T2D, there is an inverse relationship between IGFBP-1 and insulin however, a parallel upward shift in the regression line is observed, compared to pre-diabetes." (PMID 39595651, 2024). "RBC (p = 0.012), AlAt, C-peptide (both p < 0.001) were higher whereas SHBG (p = 0.002), adiponectin and IGFBP-1 (both p < 0.001) were lower in individuals with prediabetes/diabetes in comparison with individuals with normal glucose tolerance." (PMID 35439985, 2022). "Whereas, low serum IGFBP-1 levels and increased DNA methylation levels in the IGFBP-1 gene were associated with the risk of type 2 diabetes (T2D), implies that IGFBP-1 is involved in different types of diabetes by different mechanisms." (PMID 35002740, 2021). "Reduction of IGFBP1 in diabetes through both insulin-dependent and insulin-independent pathways is a novel mechanism by which carnosine contributes to the improvement of the metabolic control in diabetes." (PMID 34203479, 2021). "We demonstrate that deletion of IGFBP-1 does not modulate metabolic phenotype in lean or obese mice, drawing into question the argument that low levels of IGFBP-1 are permissive for the development of diabetes in humans." (PMID 32190801, 2020). "Collectively, these data suggest that low levels of IGFBP-1 are permissive for the development of both diabetes and cardiovascular disease." (PMID 32190801, 2020). "Human studies suggest that low levels of IGFBP-1 are permissive for the development of diabetes and cardiovascular disease." (PMID 32190801, 2020). "This age- and diabetes-dependent increase in IGFBP-1 and subsequent decrease in IGF-I activity accelerate endothelial cell death and reduce the regenerative capacity of these cells, offering a possible mechanism for the development of vascular complications." (PMID 26858687, 2016). "We found that IGFBP1 DNA methylation levels were higher in both newly diagnosed and treated type 2 diabetes patients with a mean diabetes duration of 3 years compared with subjects with normal glucose tolerance (19.8% and 20.2% vs. 16.9%, P < 0.001 for both)." (PMID 24246027, 2013). "Similar to women, who develop diabetes, the regression line of IGFBP1 on insulin in women born SGA was suppressed below that in women with normal OGTT over a decade." (PMID 23781317, 2013). "Kidney IGF-Iand IGF-binding protein 1 (IGFBP-1) mRNA expression increasedafter 10 and 30 days of diabetes." (PMID 12546279, 2002). "Given that patients with PAD often have comorbid metabolic disorders such as diabetes, IGFBP-1 may serve as an integrated biomarker reflecting broader cardiovascular and metabolic health." (PMID 40710778, 2025). "In these papers, low serum IGFBP-1 concentration was associated with the components of metabolic syndrome and predicted the development of diabetes; however, other studies did not support these data." (PMID 41226444, 2025). "Furthermore, our proteomic results revealed a significant reduction in the levels of MERTK (beyond the insulin receptor) and IGFBP1, leading to decreased insulin sensitivity and triggering IR and diabetes." (PMID 39840062, 2024). "The patients with poor 7-year functional outcome were older and had a larger proportion of severe strokes, diabetes, previous strokes, and sedentary lifestyle compared to the patients with favorable outcome, and they also displayed higher levels of s-IGFBP-1, HOMA-IR, and hs-CRP." (PMID 38732147, 2024). "In this extensive study, it was also reported that high baseline s-IGFBP-1 levels in a cohort without baseline diabetes (n = 1190) were associated with a reduced risk of developing type 2 diabetes over 10 years." (PMID 37298072, 2023). "IGFBP-1, IGFBP-3, IGFBP-4 are closely associated with diabetes and diabetic nephropathy." (PMID 35002740, 2021).
diabetes (continued). "Strategies to maintain IGFBP-1 levels in diabetes may support podocyte function and be therapeutically beneficial." (PMID 33758952, 2021). "Finally, metabolic abnormalities especially diabetes mellitus would influence the levels of IGF-1/IGFBP-1." (PMID 35127852, 2021). "IGFBP-1 plays an important role in diabetes and diabetic nephropathy." (PMID 35002740, 2021). "It seems likely that IGFBP1 and IGFBP2 have a beneficial effect on the risk of developing diabetes." (PMID 34371941, 2021). "Failure of IGFBP-1 deletion to alter metabolic phenotype suggests that IGFBP-1 is not essential for normal metabolic physiology, and that loss of IGFBP-1 activity is not causally implicated in susceptibility to diabetes of humans with low IGFBP-1 levels." (PMID 32190801, 2020). "We have also shown that IGFBP-3 and IGFBP-1 predict mortality and diabetes, respectively." (PMID 32492897, 2020). "Similarly, a correlation was seen between IGFBP1 DNA methylation levels and duration of diabetes in T1D patients (r = 0.240; P < 0.001) and T1D patients with or without DN (r = 0.580 and 0.425; P < 0.001 for both)." (PMID 24904693, 2014). "Details of cardiometabolic conditions, e.g., diabetes, which may have influenced the associations between IGFBP-1 and trajectories of BMI or WHtR, were not available for inclusion in the models." (PMID 40188287, 2025). "Interestingly, increases in Log10-s-IGFBP-1 retained statistical significance in all models, whereas the association with Log10-HOMA-IR was attenuated below the significance level by adjustment for hs-CRP or diabetes." (PMID 38732147, 2024). "Similarly, Igfbp1, an important regulator of insulin like growth factor 1 (IGF1) activity, showed an almost five-fold increase in SO-HFD versus HFD livers: increased hepatic expression of Igfbp1 is associated with diabetes." (PMID 26200659, 2015). "However, IGFBP-1 expression was decreased up to 33% by diabetes in the wild type mice (P<0.05)." (PMID 23028588, 2012). "Adjustments were made for sex and age (Model 1), cardiovascular risk factors (Model 2), and additionally for either BMI-category, s-IGFBP-1, HOMA-IR, diabetes, or hs-CRP." (PMID 38732147, 2024). "In the ‘Woroniecka Diabetes Glom’ dataset, IGFBP-1, -2 and -5 were downregulated in the glomeruli of diabetic individuals, with IGFBP-1 being the most highly downregulated gene (−3.83 fold change, p = 9.6 × 10−4)." (PMID 33758952, 2021). "However, when body mass index (BMI) and insulin levels were added to the model, the association between IGFBP-1 and diabetes was attenuated and no longer significant (HR 0.47, 95% CI 0.21–1.03, p = 0.06 in the overall cohort; HR 0.66, 95% CI 0.26–1.67, p = 0.38 in men)." (PMID 32492897, 2020). "Using a multiple regression model, we showed that the increased levels of IGFBP1 and TG are strong predictors of a rise in circulating ANGPTL4, which consequently indicates a state of nephropathy in people with diabetes." (PMID 31772941, 2019). "In this regard, the multiple regression model indicates that increased levels of IGFBP1 and TG are strong predictors of a rise in circulating ANGPTL4, which consequently indicates a state of nephropathy in people with diabetes." (PMID 31772941, 2019). "Circulating IGFBP-1 concentration and its interaction with IGF-I were identified as important determinants of the development of glucose intolerance or diabetes in 615 individuals studied over 4.5 years." (PMID 30392760, 2019). "IGFBP-1 is considered to be the principal acute regulator of IGF-I bioactivity and plays an important role in the development of diabetes and complications." (PMID 24904693, 2014). "Insulin-like growth factor binding protein 1 (Igfbp1; 3.8 fold increased) is overexpressed in early-stage STZ-induced diabetes in rats, and is involved in the early renal hypertrophic response." (PMID 24827579, 2014).
diabetes (continued). "In women who go on develop diabetes 8 years later, IGFBP-1 concentrations are low relative to insulin levels, perhaps due to a novel inhibitor of IGFBP-1." (PMID 26237614, 2014). "In type 1 diabetes mellitus (T1DM), low concentrations of IGF1 and high concentrations of IGF-binding protein 1 (IGFBP1) have been reported." (PMID 24327601, 2014). "The regression line for IGFBP1 on insulin in the term SGA women was suppressed below the reference material by −1 s.d., a pattern previously noticed in women who later developed diabetes." (PMID 23781317, 2013). "The effect of diabetes on mRNA expression at each time point varied among IGF1R, IGFBP1, IGFBP2, and IGFBP3." (PMID 23878504, 2013). "Poor diabetes control predicted lower IGF-1 (r2 = 0.21) and greater IGFBP-1 (r2 = 0.39), IGFBP-5 (r2 = 0.38), and bone-specific alkaline phosphatase (BALP; r2 = 0.41, p < 0.05)." (PMID 18665784, 2008). "A model including only clinical variables (maternal age, gravidity, family history of diabetes, maternal BMI, gestational week at blood sampling) without IGFBP1 levels yielded an ROC AUC of 0.66." (PMID 38627562, 2024). "Prevention of advanced glycation end products accumulation in the STZ-induced model of diabetes has been reported to inhibit overexpression of IGF1, IGFBP-1, and IGFBP-4 mRNAs, suggesting the role of glycation end products in activation of IGF1 renal expression in diabetes mellitus." (PMID 34943879, 2021). "In diabetes, including GDM, increased insulin levels may potentially lead to decreased levels of IGFBP-1." (PMID 33375174, 2020). "Taken altogether, at a condition of diabetes both with and without nephropathy, IGFBP1 was found as a marker and a significant predictor with the dependent variable ANGPTL4." (PMID 31772941, 2019). "In this study, we wanted to explore a potential correlation between IGFBP1 and ANGPTL4 under conditions of T2D alone and DN, where a rise in ANGPTL4 levels would be permissive for the development of a kidney condition as a complication of diabetes." (PMID 31772941, 2019). "Taken altogether, at a condition of diabetes both with and without nephropathy, IGFBP1 was found to be a marker and a significant predictor with the dependent variable ANGPTL4." (PMID 31772941, 2019). "Our data shows an increase in circulating IGFBP1 in people with diabetes, both with and without nephropathy." (PMID 31772941, 2019). "Increased ANGPTL4 levels correlated positively with IGFBP1 in people with diabetes with and without nephropathy." (PMID 31772941, 2019). "Although our CKDu population was not diagnosed with diabetes, the IGFBP1 was most down regulated in the early stage CKDu, more so even than the CKD groups." (PMID 28103909, 2017). "We measured the IGFBP-1, -2, -3, -6, and -7 levels in 3662 serum samples from our ongoing Phenome and Genome of Diabetes Autoimmunity (PAGODA)/Prospective Assessment in Newborns for Diabetes Autoimmunity (PANDA) study." (PMID 26858687, 2016). "Overexpressed IGFBP-1 in transgenic mice shows that its increase produces hyperinsulinaemia accompanied by glucose intolerance, and that this process is dependent upon IGFBP-1 phosphorylation state—which is increased in diabetes." (PMID 26733412, 2016). "Newly diagnosed patients with a family history of diabetes (FHD) had higher IGFBP1 methylation levels than those without FHD (20.3% vs. 18.6%, P = 0.017)." (PMID 24246027, 2013). "To understand whether IGFBP1 DNA methylation and serum IGFBP-1 levels are related to a family history of diabetes (FHD), we carried out comparison analyses between subjects with and without FHD." (PMID 24246027, 2013). "Also, in type 2 diabetes mellitus, the levels of IGF-1, IGFBP-3 and IGFBP-1 may be extremely variable." (PMID 39444449, 2024). "Additionally, s-IGFBP-1 was higher in patients with diabetes than in patients without diabetes in the acute phase, as well as after three months." (PMID 37298072, 2023).
diabetes (continued). "IGFBP-1 levels were not significantly different between patients with or without diabetes (p = 0.5230 for the AL group and p = 0.6708 for the PR group) and between those with a BMI ≥ 30 kg/m2 and those with a BMI < 30 kg/m2 (p = 0.6985 for the AL group and p = 0.2001 for the PR group)." (PMID 33436773, 2021). "According to our previous study in Swedish middle-aged and elderly twins, heredity estimates were only 36% for serum IGFBP-1 levels, which implied that nongenetic factors may contribute to the varied IGFBP-1 levels in diabetes." (PMID 24904693, 2014). "Diabetes did not alter the mRNA expression of IGF1R or IGFBP1 (p>0.15)." (PMID 23878504, 2013). "However, more recently, studies reported that IGFBP1 affects the prognosis and mortality of cardiovascular diseases in patients without diabetes and glucose intolerance, which might be due to an independent direct regulation of vascular endothelial cells (EC) and smooth muscle cells (SMC)." (PMID 28316362, 2017). "Diabetes increased the expression of IGFBP2 after 12 weeks and IGFBP3 after 4 and 12 weeks, but did not change the expression of IGF1R or IGFBP1." (PMID 23878504, 2013).